Y_RNA (Y RNA )
Gene: Miscellaneous RNA gene on chromosome X (123,857,062 to 123,857,163, reverse strand). Ensembl gene ENSG00000199705.
Homologues: Orthologues: chimpanzee Y_RNA (99% identical), macaque Y_RNA (95% identical). Paralogues in human: Y_RNA (90% identical), RNY3 (89% identical), RNY3P1 (87% identical), Y_RNA (87% identical), Y_RNA (86% identical), Y_RNA (85% identical), RNY3P14 (84% identical), Y_RNA (84% identical), RNY3P11 (83% identical), Y_RNA (83% identical), Y_RNA (82% identical), Y_RNA (81% identical), and 95 more.